EGFR (epidermal growth factor receptor)
Diseases named in the same sentence as EGFR in open-access papers (continued):
Sharing a sentence is not in itself a finding about the gene and the disease.
non-small cell lung carcinoma (continued). "A study of non-small-cell lung cancer reported that baseline EGFR levels and serum changes in EGFR levels during therapy were associated with response to gefitinib and progression-free survival." (PMID 23990977, 2013). "We report 23% incidence of Epidermal growth factor receptor (EGFR) mutations in 907 Non small cell lung cancer (NSCLC) patients of Indian ethnicity, in contrast to 10–15% known in Caucasians and 27–62% among East Asians." (PMID 24124538, 2013). "Icotinib hydrochloride is effective especially in EGFR mutation carriers and well tolerated in patients with recurrent advanced non-small-cell lung cancer." (PMID 23676980, 2013). "Erlotinib, the epidermal growth factor receptor (EGFR)-targeting tyrosine kinase inhibitor, has been approved for localized as well as metastatic non-small cell lung cancer where it seems to be more effective in patients with EGFR mutations." (PMID 23407898, 2013). "Treatment with epidermal growth factor receptor (EGFR) tyrosine kinase inhibitors (TKIs) has been associated with favorable progression free survival (PFS) in patients with non-small cell lung cancers (NSCLC) harboring EGFR mutations." (PMID 24376677, 2013). "Epidermal growth factor receptor tyrosine kinase inhibitors (EGFR-TKIs) are routine treatments for non-small cell lung cancer (NSCLC) with EGFR mutation." (PMID 24113003, 2013). "Activating epidermal growth factor receptor (EGFR) mutations are recognized biomarkers for patients with metastatic non-small cell lung cancer (NSCLC) treated with EGFR tyrosine kinase inhibitors (TKIs)." (PMID 24039832, 2013). "Epidermal growth factor receptor (EGFR) gene mutation is the most important predictor of the efficiency of EGFR-tyrosine kinase inhibitors in the treatment of non-small cell lung cancer (NSCLC)." (PMID 23327870, 2013). "An increased risk of progression in the CNS was found in advanced non-small cell lung cancer with EGFR mutations." (PMID 23344048, 2013). "Epidermal growth factor receptor (EGFR) mutations in non-small-cell lung cancer (NSCLC) are predictive of response to treatment with tyrosine kinase inhibitors." (PMID 24364033, 2013). "For example, the strong effects of epidermal growth factor receptor tyrosine kinase inhibitors (EGFR-TKIs; i.e., gefitinib and erlotinib) on non-small-cell lung cancer (NSCLC) are correlated with activating somatic mutations in EGFR." (PMID 24278442, 2013). "Of interest, EGFR inhibitors are currently used in clinics for non-small cell lung cancer patients with EGFR activating mutations and RAB25 expression has been reported to correlate positively with EGFR inhibitor sensitivity in NSCLC cell lines." (PMID 24216980, 2013). "Perhaps the best model for EGFR mutation-driven tumorigenesis is in non-small cell lung cancer where activating mutations within exons 18-21 of EGFR have been reported and predict for response to EGFR inhibitors." (PMID 24260133, 2013). "In patients with advanced non-small cell lung cancer, activating mutations in the EGFR gene confer hypersensitivity to the tyrosine kinase inhibitors, gefitinib and erlotinib." (PMID 24137394, 2013). "Deletions or insertions in exon 19 and point mutations in exons 18 and 21 in the epidermal growth factor receptor are special diagnostic value in advanced-stage non-small cell lung cancer patients." (PMID 23706092, 2013). "The effect of EGFR tyrosine kinase inhibitors (TKI) in patients with non-small-cell lung cancer (NSCLC) depends on the EGFR mutation status." (PMID 23922984, 2013). "Examples in treatment of solid tumors include ERBB2 (HER2) gene amplification in breast and gastric cancer, EGFR mutation in non-small cell lung cancer, and KRAS mutation in colorectal cancer." (PMID 23700467, 2013). "Epidermal growth factor receptor (EGFR) is occasionally mutated in non-small cell lung cancer and heterogeneity in treatment response results from different EGFR mutations." (PMID 23232551, 2013).
non-small cell lung carcinoma (continued). "Previous studies have shown that certain non-small cell lung cancer (NSCLC) patients harbor gain-of-function mutations in the epidermal growth factor receptor gene (EGFR)." (PMID 23403410, 2013). "To date, a small number of pharmacogenetic studies have identified EGFR polymorphisms as potential biomarkers in predicting response to anti-EGFR therapies in mCRC and non-small cell lung cancer." (PMID 23356214, 2013). "EGFR is overexpressed in various solid tumors including breast, colorectal, ovarian and non-small-cell lung cancer, and excessive EGFR signaling is associated with the development of a wide variety of benign and metastatic tumors." (PMID 23706036, 2013). "Epidermal growth factor receptor (EGFR) tyrosine kinase inhibitors (TKIs), routinely used to treat advanced non-small-cell lung cancer (NSCLC) patients with activated EGFR mutations, are associated with excellent response and improved performance status." (PMID 23566546, 2013). "Recently, pharmacological treatment of non-small cell lung cancer (NSCLC) has undergone a major change for patients with somatic mutations in the tyrosine kinase domain of the epidermal growth factor receptor (EGFR) gene." (PMID 24376508, 2013). "From January 2011 through April 2012, a total of 484 patients with non-small cell lung cancer were tested for EGFR mutations." (PMID 23590575, 2013). "Several independent groups have investigated the sensitivity and specificity of these antibodies in the detection of EGFR mutations in non-small cell lung cancer (NSCLC)." (PMID 23419122, 2013). "Studies have showed that the kinase domain mutations of the EGFR gene in the non-small-cell lung cancer (NSCLC) tissues correlate with clinical responses to gefitinib." (PMID 24103528, 2013). "We demonstrate this structure with clinical trial reports on non-small cell lung cancer (NSCLC) with an epidermal growth factor receptor (EGFR) mutation." (PMID 23920679, 2013). "Somatic mutations of the epidermal growth factor receptor (EGFR) are reportedly associated with various responses in non-small cell lung cancer (NSCLC) patients receiving the anti-EGFR agents." (PMID 23590575, 2013). "The aim of this study is to evaluate the relationship between EGFR mutation status in serum and predicting benefit from EGFR-TKIs therapy in patients with advanced non-small cell lung cancer (NSCLC)." (PMID 23769345, 2013). "Recent studies have seen rapid evolution of drug resistance in cancers which occur due to mutations in the epidermal growth factor receptors (EGFR), including non-small-cell lung cancer (NSCLC) and colorectal cancers." (PMID 23745144, 2013). "We previously reported that non-small cell lung cancer (NSCLC) cells which harbor epidermal growth factor receptor (EGFR) mutations display elevated VDR expression (VDRhigh) and are vitamin D-sensitive." (PMID 24217116, 2013). "Mutations in EGFR have been implicated in the pathogenesis of another brain metastasis-giving tumor type, the non-small cell lung carcinoma." (PMID 23344048, 2013). "The epidermal growth factor receptor (EGFR) is a well-characterized mutated oncogene in non-small cell lung cancer (NSCLC) that is found in ~10–20% of cases in western countries and is associated predominantly with adenocarcinoma histology." (PMID 22970367, 2012). "The epidermal growth factor receptor (EGFR) inhibitor, gefitinib, has been reported to successfully treat advanced non-small cell lung cancer patients with genetic mutations in EGFR." (PMID 22252115, 2012). "We have considered current methods chronologically reported to detect mutations in epidermal growth factor receptor in patients with non-small cell lung cancer." (PMID 23232076, 2012). "For example, pooled CTCs have been assayed for HER2 in breast cancer using FISH, TMPRRSS2-ERG rearrangements in prostate cancer using RT-PCR and EGFR mutations in non-small cell lung cancer." (PMID 23145101, 2012).
non-small cell lung carcinoma (continued). "Although non-small cell lung carcinoma with an activating EGFR mutation, L858R, responds well to gefinitib and erlotinib, tumors with a doubly mutated EGFR, T790M-L858R, acquire resistance to these drugs." (PMID 22957020, 2012). "Gefitinib, a tyrosine kinase inhibitor, is an effective treatment in advanced non-small cell lung cancer (NSCLC) patients with an activating mutation in the epidermal growth factor receptor (EGFR)." (PMID 22963131, 2012). "In recent years, gefitinib, an epidermal growth factor receptor tyrosine kinase inhibitor, has brightened the outlook for patients with advanced non-small cell lung cancer, especially for those who carry epidermal growth factor receptor-activating mutations." (PMID 23079208, 2012). "Non-small-cell lung cancer harboring epidermal growth factor receptor (EGFR) mutations attains a meaningful response to EGFR-tyrosine kinase inhibitors (TKIs)." (PMID 22815900, 2012). "Hypophosphorylation of Tyr1045 has been reported in non-small cell lung cancers (NSCLCs) bearing EGFR mutations in the tyrosine kinase domain and in an EGFRvIII variant bearing an internal in-frame deletion in the extracellular domain." (PMID 22591401, 2012). "Many different methods were developed to detect commonly known mutations and to screen new mutations of the epidermal growth factor receptor in non-small cell lung cancer patients." (PMID 23232076, 2012). "We report the case of a patient with an orbital non-small cell lung cancer metastasis with epidermal growth factor receptor-activating mutations." (PMID 23079208, 2012). "In non-small cell lung cancer, epidermal growth factor receptor gene mutations and anaplastic lymphoma kinase (ALK) gene rearrangements have a major impact upon the level of response to treatment with specific tyrosine kinase inhibitors." (PMID 22825000, 2012). "The EGFR tyrosine kinase inhibitors, gefitinib and erlotinib, are considered active agents in a subset of patients with non small-cell lung cancer harboring EGFR-mutations and seems to be effective in the treatment of brain metastases." (PMID 23412694, 2012). "The EMEA approved gefitinib for the treatment of non small cell lung cancer for patients carrying an activating EGFR mutation in 2009." (PMID 22397594, 2012). "Uncommon for EGFR mutations in non-small cell lung cancer the female patient presented here was of older age." (PMID 23088930, 2012). "Patients with non-small cell lung cancer (NSCLC) harboring mutations in the epidermal growth factor receptor (EGFR) gene have dramatic response to the EGFR- tyrosine kinase inhibitor (EGFR-TKI)." (PMID 23181703, 2012). "It has been proven that epidermal growth factor receptor-tyrosine kinase inhibitor (EGFR-TKI) significantly benefits advanced non-small cell lung cancer (NSCLC) patients harboring EGFR mutations in progression-free survival time with better tolerance." (PMID 22613337, 2012). "Non-small cell lung cancer patients with L858R or exon 19 deletion mutations in EGFR show good responses to the tyrosine kinase inhibitor gefitinib." (PMID 22343623, 2012). "Patients with non-small cell lung cancer (NSCLC) show 30% EGFR mutations and 5% ALK translocations, which are driver mutation targeted by molecular target agents such as Gefitinib or ALK inhibitors." (PMID 22043994, 2012). "Non-small cell lung cancers harboring an EGFR activating mutation can show primary resistance to EGFR TKI therapy." (PMID 22970367, 2012). "The epidermal growth factor receptor (EGFR) is overexpressed in 80% of non-small cell lung cancer (NSCLC) and is associated with poor survival." (PMID 22087216, 2011). "Somatic EGFR mutations have been reported to be the genetic events underlying responsiveness of non-small cell lung cancer to the small molecular EGFR-inhibitor gefitinib." (PMID 22152101, 2011).
non-small cell lung carcinoma (continued). "Non-small cell carcinoma that harbor an activating mutation in the epidermal growth factor receptor (EGFR) kinase domain are associated with sensitivity to tyrosine kinase inhibitor (TKIs)." (PMID 29147262, 2011). "We performed this retrospective study to assess the association of epidermal growth factor receptor (EGFR) with metastatic presentations in advanced non-small cell lung cancer (NSCLC)." (PMID 22091430, 2011). "EGFR mutations have been found to occur in 13% to 64% of all non-small cell lung cancers and exon 19 deletions and L858R mutations account for >80% of all EGFR mutations detected in NSCLC." (PMID 21457545, 2011). "More recently, the EGFR tyrosine kinase inhibitor gefitinib has been approved for treatment of non-small-cell lung cancer (NSCLC) patients that carry mutations of the EGFR gene." (PMID 22216189, 2011). "EGFR is implicated in the development of many human cancers, as activating mutations of EGFR have been identified in human glioblastoma, non-small cell lung carcinomas (NSCLC), and colon cancer." (PMID 21949687, 2011). "Epidermal growth factor receptor (EGFR) mutation is strongly associated with the therapeutic effect of tyrosine kinase inhibitors (TKIs) in patients with non-small-cell lung cancer (NSCLC)." (PMID 22142557, 2011). "Non-small cell lung cancer (NSCLC) with mutations in the epidermal growth factor receptor (EGFR) is a distinct subgroup of NSCLC, which is particularly responsive to EGFR tyrosine kinase inhibitors (TKIs)." (PMID 21342642, 2011). "For non-small-cell lung cancer, the population approved for gefitinib is defined by the presence of specific EGFR mutations, whereas for colorectal cancer, patients with KRAS mutations are excluded from treatment by cetuximab." (PMID 21966417, 2011). "EGFR is frequently overexpressed in various human tumors including non-small-cell lung cancer (NSCLC) and is associated with poor outcome." (PMID 21333004, 2011). "The aim of this study is to investigate the association between single nucleotide polymorphism rs2293347 in EGFR and the clinical outcome in patients with advanced non-small cell lung cancer (NSCLC) treated with gefitinib." (PMID 21859544, 2011). "The modified restriction enzyme-based method is convenient for clinical EGFR mutation screening in non-small cell lung cancer for its simpleness, cost-saving and high sensitivity." (PMID 21859543, 2011). "In non-small cell lung cancers, EGFR mutations, wild-type KRAS, and EGFR amplification have been described as predictive marker of erlotinib efficacy." (PMID 24212636, 2011). "The sensitivity of non-small cell lung cancer (NSCLC) patients to EGFR tyrosine kinase inhibitors (TKIs) is strongly associated with activating EGFR mutations." (PMID 21731744, 2011). "K-Ras, LKB1 and epidermal growth factor receptor (EGFR) are frequently mutated in non-small cell lung cancer (NSCLC)." (PMID 21695126, 2011). "Mutations of EGFR and K-ras are biomarkers for predicting the efficacy of targeting agents in non-small-cell lung cancer (NSCLC) and colorectal cancer (CRC)." (PMID 20184776, 2010). "Results of the phase II LUX-Lung-2 study focusing on patients with EGFR-mutated non-small cell lung cancer have been reported and demonstrated a 61% response rate, PFS of 14 months and median survival of 2 years." (PMID 21165163, 2010). "At a clinical level, gefitinib and erlotinib for TKI, are used in the treatment of non-small cell lung cancer, where they were found to be particularly effective in patients with certain EGFR mutations." (PMID 27713352, 2010). "Activating mutation in exons 18, 19 and 21 of the EGFR gene has proved to be a significant factor in predicting response to EGFR-TKIs in non-small cell carcinoma of the lung." (PMID 20664595, 2010). "EGFR mutation status was analyzed by DNA assays, and compared with IHC results in five non-small-cell lung cancer (NSCLC) cell lines and tumor samples from 78 stage IV NSCLC patients." (PMID 21167064, 2010).
non-small cell lung carcinoma (continued). "Several subtypes of common cancers have been identified based on the aberrations of individual cancer genes, for example HER2-amplified breast cancer, EGFR-mutated and EGFR-amplified non-small-cell lung cancer, and others." (PMID 20569491, 2010). "In non-small cell lung cancer, mutations in the TK domain of the EGFR have been shown to be associated with a high treatment response rate to the EGFR TK inhibitor erlotinib." (PMID 21063399, 2010). "The NEJ002 study was prematurely closed after accruing 230 patients due to a significant benefit seen for gefitinib versus carboplatinum/paclitaxel in patients with prospectively identified EGFR-mutated advanced non-small cell lung cancer." (PMID 21165163, 2010). "In non-small cell lung cancers, EGFR mutations were significantly associated with a good prognosis in patients that had tumors with unmethylated Wnt antagonist genes, suggesting synchronous alterations of Wnt and EGFR signaling pathways are involved." (PMID 20828404, 2010). "The WJTOG3405 study enrolled 177 chemotherapy-naïve patients aged 75 years or younger and diagnosed with stage IIIB/IV non-small cell lung cancer or postoperative recurrence harboring EGFR mutations- either exon 19 deletions or L858R." (PMID 21165163, 2010). "Patients with non-small cell lung cancer whose tumors harbor an EGFR mutation have a superior response to TKI therapy compared with chemotherapy alone." (PMID 20961434, 2010). "Well-established examples include KIT mutations in gastrointestinal stromal tumors (GISTs) that predict response to imatinib or nilotinib, and non-small cell lung cancers with EGFR mutations that are sensitive to erlotinib." (PMID 19924296, 2009). "Activating mutations within the epidermal growth factor (EGFR) tyrosine kinase domain identify non-small cell lung cancer patients with improved clinical response to tyrosine kinase inhibitor therapy." (PMID 19174819, 2009). "For example, EGFR mutations predictive of response to erlotinib and gefitinib were identified at the expected frequency (12%) in non-small cell lung cancer, and KIT mutations linked to sensitivity to imatinib and nilotinib were detected in 76% of GISTs." (PMID 19924296, 2009). "Approximately 10% of patients with non-small cell lung cancer (NSCLC) (those harboring an activating mutation of EGFR) show a dramatic shrinkage in response to the inhibitor gefitinib, but this is unlikely to lead to long-term cure." (PMID 19657384, 2009). "Recently, several somatic mutations in the EGFR gene have been linked with favourable response to treatment with anti-EGFR tyrosine kinase inhibitors (TKIs), gefitinib and erlotinib, in non-small cell lung cancer (NSCLC) patients." (PMID 19401686, 2009). "In two recent trials in advanced non-small cell lung cancer, therapy with gefitinib administered in a genotype-directed fashion to patients harbouring EGFR mutations resulted in very favourable clinical outcomes with good tolerance." (PMID 19174819, 2009). "In non-small-cell lung cancer, EGFR mutation and/or amplification have been reported as possible predictive factors of sensitivity to EGFR tyrosine kinase inhibitors." (PMID 19319137, 2009). "The exon 19 deletions and L858R in exon 21 represent 85–90% of EGFR mutations in non-small cell lung cancer." (PMID 19174819, 2009). "In non-small cell lung cancer the presence of mutations in the tyrosine kinase domain of EGFR observed in a minority of patients with adenocarcinoma, is a critical determinant for tumour response to tyrosine kinase inhibitors." (PMID 18182111, 2008).